TNF (tumor necrosis factor)
Diseases named in the same sentence as TNF in open-access papers (continued):
Sharing a sentence is not in itself a finding about the gene and the disease.
periodontitis (continued). "Thus, our results may indicate that P. gingivalis stimulates apoptosis of fibroblasts through a less extensive degradation of TNF-α and this could account for the fibroblast apoptosis that is a distinctive feature of periodontitis." (PMID 23841502, 2013). "Specific soluble receptors (antagonists) of IL-1 and TNF-α inhibited the progression of bone loss by reducing the formation of osteoclast and recruitment of inflammatory cells in a nonhuman primate experimental periodontitis model." (PMID 22315682, 2012). "Many researchers investigated the possible link between the -308 polymorphism in the TNF-α gene and periodontitis because a G to A polymorphism at the -308 position of the TNF-α promoter region was suggested to influence TNF-α production and monocytes of patients with periodontitis." (PMID 23046796, 2012). "In the present study, MKE significantly decreased the levels of key inflammatory mediators such as iNOS, TNF-α, IL-6, IL-1β, COX-2, and mPGES-1 in the periodontitis-induced rat model." (PMID 41614939, 2026). "At baseline, TNF-α and TLR-2 levels were significantly higher in periodontitis patients compared with healthy controls (p < 0.001)." (PMID 42154854, 2026). "Periodontitis patients before and 1 year present with similar levels of MCP‐1, TNF‐α, and IL‐6, cytokine equilibrium." (PMID 41580300, 2026). "MLKL-mediated necroptosis in macrophages promotes the upregulation of TNF-α, IL-1β, IL-6, COX-2 and MMP9, contributing to alveolar bone resorption in mouse periodontitis models." (PMID 40307566, 2025). "Concurrently, host neutrophils in periodontitis lesions exhibit hyperactivation, secreting chemokines (e.g., CXCL8) and cytokines (e.g., TNF-α and IL-1β), which amplify monocyte recruitment and chronic inflammation." (PMID 41009952, 2025). "Increased concentrations of IL-1β, TNF-α, and VEGF have also been observed in Grade C sites of Stage III periodontitis, reinforcing the link between cytokine expression and disease aggressiveness." (PMID 41440349, 2025). "Tumor necrosis factor alpha (TNF-α), interleukin-1 beta (IL-1β), and interleukin-6 (IL-6) are critical cytokines in the etiology of periodontitis." (PMID 40564062, 2025). "The results showed that PA significantly reduced IL-1β, IL-6, TNF-α, CRP, and LPO levels and increased IL-10 levels in the periodontitis group; moreover, the histological analysis showed reduced inflammatory infiltrate and less fiber degradation." (PMID 40422620, 2025). "This study compared tumor necrosis factor-α (TNF-α) and interlukin-1β (IL-1β) concentrations in the saliva and gingival crevicular fluid (GCF) of patients with gingivitis and periodontitis and healthy individuals." (PMID 40265034, 2025). "Four weeks after treatment, the correlations between TNF-α and leptin, adiponectin, resistin, FFA, the gingival bleeding index, and periodontitis grade were significantly greater (P < 0.05)." (PMID 41244040, 2025). "In this study, baseline mean TNF-α levels were 59.88 pg/ml in Group I (Healthy), 78.40 pg/ml in Group II (Periodontitis), and 111.18 pg/ml in Group III (Periodontitis with T2DM)." (PMID 41280962, 2025). "More studies are needed to investigate the role of other inflammatory cytokines (besides IL-1β), such as TNF-α, IL-6, RANKL, and OPG, in the inflammatory reaction of induced periodontitis and subsequent alveolar bone resorption." (PMID 40692535, 2025). "Furthermore, leveraging this physiological model, we simulated periodontitis-induced effects on the vascular barrier and downstream bone tissue by applying P. gingivalis metabolite LPS (direct action) and pro-inflammatory cytokine TNF-α (indirect action via circulation)." (PMID 41427424, 2025). "We found that UA reduced IL-6 and TNF-α levels in vitro and in vivo, inhibited osteoclast differentiation, and decreased the RANKL/OPG ratio in periodontitis mice." (PMID 40649395, 2025).
periodontitis (continued). "This chronic inflammatory state is primarily driven by cytokines or mediators including TNF-α, IL-1β, and PGE2, which are upregulated in both human periodontitis and EPD models." (PMID 41154468, 2025). "This study aims to evaluate the independent effects of periodontitis on TMAO and TNF-α levels in saliva and serum." (PMID 40131489, 2025). "TNF‐α, IL‐1, and PGE2 also stimulate osteoclast activity, especially in inflammatory conditions characterized by osteolysis, such as those observed in periodontitis." (PMID 40761494, 2025). "Pearson’s correlation coefficient also showed a direct and significant relationship between TNF-α and IL-1β salivary and GCF concentrations in patients with periodontitis or gingivitis." (PMID 40265034, 2025). "The findings of this study revealed that the mean concentration of TNF-α in the saliva and GCF was higher in patients with periodontitis compared to the gingivitis group and healthy individuals." (PMID 40265034, 2025). "The synergistic impact of elevated pro-inflammatory cytokines (TNF-α, IL-6, and resistin) and reduced APN disrupts insulin signaling pathways, thereby affecting periodontitis." (PMID 41246338, 2025). "The balance between TGF-β, IL-10, and TNF-α plays a key role in healing, suggesting that PRF therapy supports tissue repair and inflammation control in periodontitis patients." (PMID 40710037, 2025). "TNF-α, known to increase PGE2 concentration and activate osteoclasts, is expected to be higher in patients with periodontitis than in the gingivitis and healthy groups." (PMID 40265034, 2025). "Consistent with existing literature 45-47, periodontitis was found to elevate levels of various growth factors and inflammatory mediators, including G-CSF, IFN-γ, IFN-I, IL-1α, IL-6, and TNF-α." (PMID 40521205, 2025). "Arecent study examined the correlation of LRG in periodontitis by analysing GCF and blood concentrations of LRG, IL-6, and TNF-α inindividual with stage-3 periodontitis." (PMID 40822769, 2025). "Several pro-inflammatory cytokines, including IL-1, IL-6, IL-12, IL-17, IL-18, IL-21, TNF-α, and IFN-γ, play a critical role in the pathogenesis of periodontitis." (PMID 40136726, 2025). "The present study aimed to assess the clinico-radiographic parameters and salivary levels of RANKL, OPG, IL-6, and TNF-α around standard implant- and SDI-supported fixed partial dentures in partially dentate T2DM patients treated for periodontitis." (PMID 39625348, 2024). "The reduction of IL-1β, TNF-α, IL-6, and RANKL levels after dietary supplementation with n-3 PUFA as an adjunctive therapy for periodontitis was the most prevalent among the reviewed studies." (PMID 39661860, 2024). "Osteocalcin (OC), IL-1β, tumor necrosis factor-alpha (TNF-α), interleukin-6 (IL-6), OPG, and matrix metalloproteinase-9 (MMP-9) were significant in oral fluid or saliva, and they were from periodontitis, MRONJ, and osteoporosis." (PMID 39410587, 2024). "Specifically, IL-1β, TNF-α, IL-6, and RANKL levels were reduced after dietary supplementation with n-3 PUFA as an adjunctive therapy for periodontitis." (PMID 39661860, 2024). "Research indicates that during the early inflammatory phase of ligation-induced periodontitis, there is a higher expression of M1-related genes such TGF-β, CD80, and TNF-α mRNA." (PMID 38907216, 2024). "The explanation for the relationship is that periodontitis can activate cascades of inflammatory immune mediators, such as prostaglandin E2 (PGE2), IL-6, IL-1, and TNF-alpha, and thus be related to adverse perinatal outcomes." (PMID 38397649, 2024). "By employing IL-1β and TNF-α antagonists or knocking down the IL-1 receptor and TNF receptor, alveolar bone resorption in mice with experimental periodontitis was also decreased (Assuma, Oates, Cochran, Amar and Graves, 1998; Graves and Cochran, 2003)." (PMID 38347915, 2024).
periodontitis (continued). "Administration of 10% CPH reduced the number of osteoclasts (p<0.05), TNF-α level on days 7 and 14 (p<0.05), and RANKL expression on day 7 (p<0.05) in experimental rats with periodontitis." (PMID 39630805, 2024). "Studies have reported increased local levels of pro-inflammatory cytokines, such as interleukin-1beta (IL-1beta), tumor necrosis factor (TNF), IL-6, IL-17, and IL-23, in patients with periodontitis." (PMID 39253090, 2024). "This study evaluated changes in inflammatory markers within GCF, including TNF-α, IL-1β, IL-6, IL-8, hs-CRP, ICAM-1, HMGB1, and PGE2, before and after treatment in patients with osteoporosis and periodontitis." (PMID 39686428, 2024). "The hub genes identified in the periodontitis comorbidity network, such as TNF, IL6, PTGS2, IL10, and NOS3, play pivotal roles in connecting periodontitis with various systemic diseases, as indicated by their high connectivity degrees." (PMID 39337647, 2024). "In their immune studies, it was found that tumor necrosis factor (TNF)-α, interleukin (IL)-6, IL-10, and tumor growth factor (TGF)-β1 were closely related to the occurrence and development of periodontitis (7-, 9)." (PMID 38265340, 2024). "C: Systemically and periodontally healthy control group, CP: chronic periodontitis group, ALP: alkaline phosphatase, OSC: osteocalcin, sRANKL: soluble receptor activator of nuclear factor-kappaB, IL-1β: interleukine-1β, TNF-α: tumor necrosis factor-α." (PMID 38646303, 2024). "Recent studies have explored the potential impact of periodontitis during pregnancy on systemic inflammatory markers such as CRP, IL-6, and tumor necrosis factor-alpha (TNF-α)." (PMID 38595889, 2024). "Pro‐inflammatory cytokines, such as interleukin (IL)‐6, IL‐1β, and tumor necrosis factor (TNF)‐α, have been identified as the key molecules leading to the development of periodontitis." (PMID 38656694, 2024). "On the other hand, in a periodontitis model, the use of SHED-derived EVs decreased the presence of IL-6 and TNF-α in inflamed areas and improved bone regeneration." (PMID 38396665, 2024). "Inflammatory cytokines, including IL-1β, IL-6, tumor necrosis factor-alpha, and chemokine (C-C motif) ligand 2 (CCL2), play a crucial role in the inflammatory response of periodontitis." (PMID 38560458, 2024). "Increased plasma levels of IL-1β, IL-6, TNF-α, CRP, MMP-8, and MMP-9 have been observed in patients with periodontitis." (PMID 38672972, 2024). "Elevated levels of cytokines such as interleukin-1β (IL-1β), tumor necrosis factor-alpha (TNF-α), and interleukin-6 (IL-6) are commonly observed in chronic periodontitis." (PMID 38910764, 2024). "CBD administered in animals subjected to experimental periodontitis and in cells stimulated by LPS from P. gingivalis reduced the levels of cytokines such as RANK, RANKL, TNF- α, IL-1β, IL-6, IL-12 p40, and IL-8." (PMID 39065590, 2024). "Treatment of periodontitis effected IL-6, LDL, HDL, TC, TG and SBP with moderate certainty of evidence while the certainty of evidence on CRP, IL-1β, TNF-α, DBP and FMD was low." (PMID 38877442, 2024). "Recent studies have suggested potential links between periodontitis during pregnancy and systemic inflammatory markers such as CRP, IL-6, and TNF-α." (PMID 38595889, 2024). "The pro-inflammatory cytokines TNF-α and IL-6 were increased in the APDC-KO mice after 3 weeks of periodontitis induction, whereas the pleiotropic cytokine IL-2, which mediates both pro- and anti-inflammatory functions, was significantly decreased." (PMID 37928259, 2023). "In this study, SRP significantly decreased the GCF levels of IL-6 and TNF-α, which supports the anti-inflammatory effect of SRP in periodontitis." (PMID 37645411, 2023). "In patients with periodontitis, the absolute number of MAIT cells in circulating blood decreased, while the proportion of CD69+ MAIT increased and the blood levels of IL-17 and TNF-α increased." (PMID 36896188, 2023).
periodontitis (continued). "IL-1β, IL-6, TNF-α and IFN-γ have been identified as key players in the pathogenesis of periodontitis." (PMID 38002398, 2023). "According to certain research, the progression of periodontitis is characterized by high concentrations of the pro-inflammatory cytokines, IL1 and TNFα, and low concentrations of IL10 and transforming growth factor β." (PMID 37570272, 2023). "Bahammam and Attia have found significantly elevated levels of IL-6, TNF-α, and visfatin in GCF of diabetic patients afflicted with chronic periodontitis." (PMID 38149100, 2023). "M2 activation reduces TNF‐α secretion in RAW 264.7 cells and decreases AB resorption in a murine periodontitis model." (PMID 36929672, 2023). "In patients with severe periodontitis, the serum concentrations of pro‐inflammatory cytokines such as IFN‐γ, IL‐2, TNF‐α, and IL‐1β are much higher than that of healthy controls, which is also observed in gingival tissue biopsies." (PMID 37647428, 2023). "According to the current findings, with the exception of individuals who only had periodontitis (G2), the patients with OSA and periodontitis and OSA had similarly low levels of TNF-α in saliva." (PMID 36967976, 2023). "Inhibition of RAGE reduced TNF-α production, which confirms the role of RAGE receptors in slowing the development of periodontitis." (PMID 36875028, 2023). "The levels of IL-6, IL-1β, TNF-α, and IFN-β secreted under the influence of P. gingivalis were lower in the StingGt periodontitis mice than in the WT periodontitis mice (p < 0.05)." (PMID 37405166, 2023). "Meanwhile, the results of this study confirm that nano-emulsion of mangosteen rind extract in a mucoadhesive gingival patch plays a role in periodontitis, where TNF-α, IL-10, and RANKL expression are the main indicators of periodontitis." (PMID 36050950, 2022). "We previously established that exosomes of inflammatory PDLSCs were rich in RANKL and TNF-α, which could promote the osteodifferentiation of macrophages, possibly via exosome-mediated intercellular communication prompted pathological bone resorption in periodontitis." (PMID 36143428, 2022). "The influence of local inflammation of periodontitis occurring in a large proportion of the oral cavity may significantly contribute to systemic inflammation mediated by C-reactive protein and main inflammatory cytokines such as tumor necrosis factor alpha, interleukin 1b and interleukin 667,68." (PMID 35922537, 2022). "The inflammatory microenvironment, with the character, upregulated tumor necrosis factor-alpha (TNF-α), interferon-gamma (INF-γ), is essential in the initiation, development, and healing of periodontitis." (PMID 35063024, 2022). "The histopathological results in all research groups showed lymphocyte cells expressing TNF-α and TGF-β1 in the mandibular gingival sulcus that had been induced by periodontitis." (PMID 35178093, 2022). "The aim of this study was to determine the effectiveness of VCO gel on the expression of TNF-α and TGF-β1 in the tissue regeneration process after periodontitis." (PMID 35178093, 2022). "Our study showed that mice with ligature-induced periodontitis exhibited a significant upregulation of IL-1, IL6, and TNF-α expression, which were downregulated by the administration of fenofibrate, compared with control experimental periodontal disease mice." (PMID 35293424, 2022). "Patients with severe periodontitis have increased levels of pro-inflammatory markers (CRP, fibrinogen, IL-6, IL-1, TNF-α) and neutrophils in the blood and effective periodontal treatment diminishes these inflammatory markers." (PMID 35052857, 2022). "Previous studies have reported that the stimulation of TNF-α induces sTNF-R2 shedding from gingival fibroblasts in vitro, and that TNF-α, sTNF-R1, and sTNF-R2 in gingival crevicular fluid (GCF) are significantly increased in chronic periodontitis." (PMID 35200250, 2022).
periodontitis (continued). "Our study showed that increases in TNF-α, IL-1, and IL6 were reduced by fenofibrate administration in the ligature-induced experimental periodontitis model." (PMID 35293424, 2022). "The aim of this study was to investigate the anti-inflammatory effects of DJLE by evaluating the inhibition of IL-1β, IL-6, TNF-α, iNOS, and COX-2 expression in hPDLCs to examine the potential to develop a treatment agent for periodontitis." (PMID 35455384, 2022). "Patients with periodontitis exhibit an elevated level of systemic pro-inflammatory mediators, which include CRP, TNFα, IL-1β, IL-6, as well as increased neutrophil numbers in the blood." (PMID 35874771, 2022). "Moreover, another study also concluded that CU decreases alveolar bone loss in experimental periodontitis in rats via suppressing the expression of RANKL/RANK/OPG and possesses anti-inflammatory properties through the reduction of pro inflammatory cytokines TNF-a and IL-6." (PMID 35453272, 2022). "Tumor necrosis factor-α (TNF-α) is a primary and initial inflammatory cytokine which is highly correlated with the pathogenesis of periodontitis." (PMID 34185172, 2022). "A search for potential markers of periodontitis onset or progression resulted in many potential candidates for such agent—among others matrix metalloproteinase (MMP)-8, IL-1, IL-6, tumor necrosis factor (TNF)-α, PGE2." (PMID 36245042, 2022). "The salivary levels of miR-1246, IL-1β, IL-6, IL-17, TNF-α, MMP-1, MMP-8, and TIMP-1 and the periodontal indexes PLI, GI, PD, and AL in the chronic periodontitis group were significantly higher than those in the healthy control (P < 0.05)." (PMID 35942384, 2022). "After classifying the severity of the periodontitis among participants it was observed that the levels of cytokines such as IFN-γ, IL-10 and TNF-α were elevated in PD." (PMID 35055157, 2022). "Many inflammatory cytokines, such as interleukin (IL)-1, IL-6, IL-17, and tumor necrosis factor (TNF)-α, play an important role in the pathogenesis of periodontitis." (PMID 36289921, 2022). "PPARα agonist decreased gingival mRNA levels of IL-1, IL-6, TNF-α, and RANKL/OPG in ligatures-induced experimental periodontitis." (PMID 35293424, 2022). "Interleukin-1β (IL-1β), IL-6, tumor necrosis factor alpha (TNF-α), and receptor activator of nuclear factor kappa B ligand (RANKL) are significant markers of the pathogenesis of periodontitis." (PMID 36050950, 2022). "An ELISA was conducted on the plasma of the healthy and periodontitis groups to measure changes in CRIP1 and IFITM1 protein concentrations, and compared with those of the inflammatory markers TNF-α, CRP, and ESR." (PMID 36329504, 2022). "Enhanced RANKL production and NF-κB signaling pathway activation by pro-inflammatory mediators, including IL-6, TNF-α, IL-1β, prostaglandin E2 (PGE2) and C3 are common in inflammatory diseases, including periodontitis and osteoporosis." (PMID 36359775, 2022). "In addition, other inflammatory mediators in periodontitis, such as IL-1β, IL-6, tumor necrosis factor-α, etc., can be secreted into the blood to activate the systemic immune response, which may lead to tissue destruction in other organs to release DAMPs-derived cfDNA." (PMID 36498477, 2022). "While we identified miR-1260b as a novel TNF-inducible GMSC-derived exosomal miRNA, miR-1260b was reported to be downregulated in gingival tissue from periodontitis." (PMID 36531939, 2022). "Interleukin- (IL-) 1β, IL-6, tumor necrosis factor alpha (TNF-α), and prostaglandin E2 (PGE2) are considered markers of the progression and severity of periodontitis and are major triggers of preterm labor." (PMID 36033560, 2022). "Immunohistochemistry confirmed the down-regulation of TNF-α and IL-6 expressions by NOD-IN-1 in P. intermedia–induced periodontitis." (PMID 36569059, 2022).